PPARG (peroxisome proliferator activated receptor gamma)
Diseases named in the same sentence as PPARG in open-access papers (continued):
Sharing a sentence is not in itself a finding about the gene and the disease.
tumor (continued). "Here, we will discuss several loss-of-function and gain-of-function mechanisms by which PPARγ can be implicated in tumor initiation and progression in several major cancers." (PMID 33716977, 2021). "In this perspective, we briefly discuss the mechanisms by which PPARγ is implicated in tumor biology as well as in the complex regulatory networks within the breast TME." (PMID 34067944, 2021). "Although the angiogenic role of PPARγ remains ambiguous, it is a crucial regulator in autocrine and paracrine signaling of cancer-associated fibroblasts and tumor-associated macrophages/immune cells." (PMID 33946986, 2021). "In our present study, PPARγ was positively associated with tumor size and poor prognosis in PDAC patients." (PMID 35186942, 2021). "Conclusively, pharmacologically diminishing tumor cells stemness transformation by targeting the CDK5/pho‐PPARγ axis causes an obvious immunophenotyping shift, thus augmenting the efficacy of anti‐PD‐1 therapy in TNBC." (PMID 33240752, 2020). "Berger and colleagues identified activation of suppressor of cytokine signaling 3 (SOCS3) by PPARγ agonists as another pathway implicated in suppression of tumor angiogenesis and growth." (PMID 32785018, 2020). "One such study showed that the tumor-suppressive function of PPARγ is associated with its regulation of lipid metabolism." (PMID 32781719, 2020). "In agreement, mice harboring a selective deficiency of PPARγ in Lysozyme-2-expressing cells (e.g., macrophages) showed impaired tumor rejection after treatment with GM-CSF-secreting and irradiated tumor cell-based vaccine (GVAX)." (PMID 32823961, 2020). "Due to the tumor-suppressive effect of PPARγ, some loss-of-function mutations in PPARG have been regarded as tumorigenic factors." (PMID 33266062, 2020). "In the same line, tumor expression of PPARγ is independently associated with increased survival of CRC patients." (PMID 33194695, 2020). "In this sense, reduced PPARγ expression within the tumor is associated with poor prognosis in lung cancer patients." (PMID 33194695, 2020). "Nonetheless, cytoplasmic PPARγ expression being much higher (15 fold) than nuclear one, total PPARγ expression exhibited similar association as cytoplasmic one with tumor aggressiveness." (PMID 32085795, 2020). "Using the established Notch tumor paradigm, we found that 20HE through Eip75B/PPARγ remote controls EB differentiation and suppresses N-loss of function driven hyperplasia." (PMID 32773037, 2020). "In patients with stages II/III CRC, polymorphism rs1801282 in PPARγ was significantly associated with tumor recurrence." (PMID 33194695, 2020). "Somewhat similarly, a recent study by Niu and collaborators shows that tumor -associated macrophage differentiation is promoted by caspase-1 cleavage of PPARγ." (PMID 31060333, 2019). "This is supported by the immunocytochemical staining results that dmrFABP5 caused significant reduction of p-PPARγ staining intensity in tumour tissues by 67%." (PMID 31258834, 2019). "The activated PPARγ then modulates the expression of its down-stream regulatory genes and these changes finally lead to enhanced tumour expansion and aggressiveness caused by an overgrowth of cells with increased angiogenesis and reduced apoptosis." (PMID 31258834, 2019). "Unlike PPARα, in some tissues, the hypoxia inducible factor downregulates PPARγ, leading to the loss of its tumor suppression activity." (PMID 29966227, 2018). "The current studies show that the ligand treatment of PPARγ inhibits the proliferation of tumor cells and induces tumor cell apoptosis, which underlines its role in tumor targeted therapy." (PMID 29483923, 2018). "An earlier study demonstrated that PPARγ is overexpressed in tumor-associated/or proliferating endothelial tissues, and TZDs selectively suppress the proliferation of endothelial cells compared to other types of cell lines." (PMID 29932104, 2018).
tumor (continued). "PPARγ agonists also prevent the myofibroblast-associated increase in collagen secretion that can result in remodeling of the tumor microenvironment and facilitate cancer pathogenesis." (PMID 28316613, 2017). "Here, we report that the PPARγ/RXRα pathway constitutes a tumor-intrinsic mechanism underlying immune evasion in MIBC." (PMID 28740126, 2017). "As increased activation of the lipogenesis pathway is a hallmark of cancer cells, PPARγ is ubiquitously expressed in many cancers and promotes lipid metabolism, glucose homoeostasis and tumor progression." (PMID 29221176, 2017). "Here we demonstrate, for the first time, that EPA and DHA supplementation prevents tumor-associated increases in the transcription expression of C/EBPδ, C/EBPα and PPARγ, and greatly mitigates further increases during chemotherapy." (PMID 28832677, 2017). "The PAX8–PPARγ rearrangement is related to the loss of the tumor suppressor function of wild-type PPARγ; however, the mechanism is not fully understood yet." (PMID 29085335, 2017). "The activated PPARγ then modulates expression of its down-stream regulatory genes which finally lead to enhanced tumour expansion and aggressiveness caused by an overgrowth of cells with increased angiogenesis and reduced apoptosis." (PMID 28415688, 2017). "Here, we report that caspase-1 promotes tumor-associated macrophage differentiation by cleaving peroxisome proliferator-activated receptor gamma (PPARγ) at Asp64, thus generating a 41 kDa fragment." (PMID 28974683, 2017). "In conclusion, we demonstrated for the first time that low PPARγ expression was significant associated with patient age, tumor number, MVI, and TNM stage in HCC patients." (PMID 27483249, 2016). "The results showed that tumor cell proliferation was significantly augmented by PPARγ-deficient macrophages compared with WT control macrophages." (PMID 27692066, 2016). "Our in vitro findings further support our in vivo observations that the increased number and pro-inflammatory property of PPARγ-deficient macrophages are sufficient to promote tumor progression." (PMID 27692066, 2016). "Mammary fat pad tumor graft experiments demonstrated that Gpr132 deletion in the DKO mice impaired the ability of macrophage PPARγ deficiency to exacerbate tumor growth because DKO mice showed similar tumor volume as Gpr132-KO mice." (PMID 27692066, 2016). "On the other hand, treatment with 27b(I) caused a robust increase of PPARγ message, which was consistent with decreased macrophage migration/recruitment to the tumor." (PMID 26161255, 2015). "Accordingly, reduction of β-catenin and PPARγ was associated with high numbers of tumor-associated macrophages, increased metastasis, and poor survival." (PMID 25866814, 2015). "The role of PPARγ activation in the progression of malignant lesions is questioned by the fact that heterozygous and homozygous intestinal-specific PPARγ deficiency promoted tumor formation." (PMID 25866814, 2015). "PPARG encodes peroxisome proliferator-activated receptor gamma (PPAR-γ/PPARG) that has tumor suppressor functions in many endocrine organs including breast, prostate and pituitary gland." (PMID 26429873, 2015). "These chemokines are under the regulation of PPARγ pathway and PPARγ ligands have been shown to inhibit tumor-associated angiogenesis by blocking the production of ELR+CXC chemokines." (PMID 25147760, 2014). "It has been documented earlier also that PPARγ can act as a tumour promoter, only in the presence of APC mutation or aberrant Wnt signaling pathway which indeed is the observation in the current study." (PMID 24999478, 2014). "Taken together, this study is the first to describe the effects of PSF on cell proliferation, tumor growth, and cell signaling associated with PPARγ." (PMID 23516550, 2013).
tumor (continued). "In order to elucidate the mechanism of PPARγ signaling in tumor development, strains of mice with defined loss-of-function mutations in the PPARγ gene were generated." (PMID 23213321, 2012). "Peroxisome proliferator-activated receptor-gamma (PPARγ) exerts compounded roles in cell differentiation, tissue metabolism and host immunity and recently is implicated in tumor suppression." (PMID 20226009, 2010). "Inactivating mutations, deletionsand chromosomal translocations of PPARγ have been found in various cancers pointing toa tumor suppressor role of this nuclear receptor." (PMID 18551186, 2008). "PPARγ induction also causes tumor cellapoptosis by downmodulating prosurvival proteins cFLIP and Bcl-2, whileincreasing proapoptotic Bax and BAD, as occurs in glioblastoma or by the interference with thePI3K/Akt signaling." (PMID 19043603, 2008). "Similar to the core loss pattern seen with COX-2 staining, the tumor size in case lesions with core loss was similar to that of control lesions with core loss during PPARγ staining (6.8 mm, range 4–20 mm in cases and 8.7 mm, range 2–20 mm in controls)." (PMID 18237383, 2008). "In summary, although its exact role in controlling lung tumor growth and apoptosisremains undefined, PPARγ has been implicated both as a tumor suppressor (inmost cases) and as a tumor promoter (in rare cases)." (PMID 18704200, 2008). "In other tumor model, we have observed that induction of PPARγ expression by BCG, 15d-PGJ2 and RGZ was associated with a decrease in NO production and loss of cell viability." (PMID 18261208, 2008). "The profile of polyamine metabolism and PPARγ mRNA expression were also investigated in relation to the presence of K-ras mutation in our tumour samples." (PMID 16854216, 2006). "Apc+/fl;Kras+/G12D;Mex3a+/- compound mice exhibited reduced tumor area, whereas corresponding tumoroids had reduced growth ability and enhanced differentiation potential associated with increased peroxisome proliferator-activated receptor gamma (PPARγ) signaling." (PMID 41881339, 2026). "Similarly, in oncology, semaglutide reprograms tumor-associated macrophages via the GLP-1R/PPARG/ACSL1 pathway, promoting M1 polarization and suppressing tumor progression." (PMID 41226200, 2025). "Specifically, the loss of tumor cell-specific PPARγ activity may be necessary for the establishment of the stromal inflammatory microenvironment that is a hallmark of neoplastic disease in the skin." (PMID 39195246, 2024). "Considering PPARG as a key regulator of adipogenesis and differentiation, it may be one of the underlying contributing factors to tumor progression and chemoresistance." (PMID 38044948, 2023). "Additionally, we sought to elucidate the association between PPARG and tumor formation, grading, and metastasis." (PMID 38044948, 2023). "The PPARG differential expression in human cancers is often associated with tumor growth." (PMID 38044948, 2023). "Studies suggest that PPARG has been associated with tumor prognosis, and maybe a therapeutic target for OSCC." (PMID 36478991, 2022). "White and brown adipose tissue express PPARγ in high concentrations, where it is believed to be involved in the mediation of numerous biological processes, including adipogenesis, glucose homeostasis, atherogenesis, inflammation, and tumor susceptibility." (PMID 35453376, 2022). "Because PPARγ has been reported to be cleaved by caspase-1 in tumor-associated macrophages 45, we tested whether the decreased PPARγ level was owing to cleavage by caspase-1." (PMID 33500734, 2021). "PPARG was further analyzed by DNA methylation, immune parameters, and tumor mutation burden." (PMID 34567087, 2021).
tumor (continued). "Both studies indicated that PPARG expression variation was significantly associated with the Tumor-Node-Metastasis (TNM) stage (p = 7.45e − 7 and 6.50e − 4, for the first and second studies, respectively), which was used as one of the predictors of chemosensitivity." (PMID 34054937, 2021). "There is also promise that PPARγ agonists could be useful for inducing differentiation of GSCs within tumours due to indications that ciglitazone and 15d-PGJ2 caused altered expression of stemness genes such as SOX2 and NANOG." (PMID 34532295, 2021). "In addition to the representative PPARγ research methods adopted in this study, further investigations of the physiological mechanisms by which PPARγ mutations influence the tumor microenvironment are needed." (PMID 33266062, 2020). "Despite the PPARγ suppresses the proliferation and tumor growth of UC, the underlying mechanism remains unclear." (PMID 33289586, 2020). "Recently, it has been reported that the well characterized miR-155, an oncomiR secreted by cancer cells, alters the metabolism of surrounding adipocytes by downregulating PPARγ expression, accelerating the cancer-lipolytic process associated with tumor progression." (PMID 33352766, 2020). "The author finishes his editorial explaining that, therefore, increased PPARG expression may be associated with decreased inflammation and would thus be predicted to result in a more indolent tumor." (PMID 32813759, 2020). "In order to focus our attention on different components of TME, we also used the following key words: “PPARγ” and “cancer-associated adipocytes”, “cancer-associated fibroblasts”; “tumor-associated macrophages”; “tumor endothelial cells”; “extracellular matrix”, “extracellular vesicles”, “exosomes”." (PMID 33352766, 2020). "Indeed, the expression of PPARγ is associated with slower progression and a lower incidence of tumor recurrence in bladder cancer." (PMID 30925918, 2019). "Moreover, a single injection of ApoSQ cells inhibited lung metastasis in syngeneic immunocompetent mice with enhanced PPARγ/PTEN signaling both in tumor-associated macrophages and in tumor cells." (PMID 30842627, 2019). "Studies have shown that activation of PPARG, γ subtype, could cause proliferation inhibition or differentiation of tumor cells." (PMID 31949474, 2019). "Previous studies demonstrate that PPARγ is expressed in a variety of tumor tissues and is closely associated with the proliferation and prognosis of digestive system tumors by its roles in mediation of cell differentiation, induction of cell apoptosis, and inhibition of cell proliferation." (PMID 29483923, 2018). "In addition, it was reported that the overexpression of PPARγ in a group of non-small lung cancer cells and its activation affect some genetic pattern underlying the tumor metabolic demands." (PMID 29966227, 2018). "This implicates that biochemical feature of PPARγ regulating nutrient metabolism might be associated with its cell biological function as a tumor suppressor." (PMID 29137280, 2017). "In addition to indirectly influencing angiogenesis through inhibition of proangiogenic factors, activation of PPARγ, which is highly expressed in tumor-associated endothelial cells, can also block angiogenesis by directly suppressing endothelial cell growth." (PMID 27698657, 2016). "The PPARγ-dependent increase in PTEN caused by PTER-ITC in our experiments not only indicates that the tumor suppressor gene contributes to the growth-inhibitory activities of the compound, but might also trigger its pro-apoptotic actions." (PMID 25119466, 2014). "This is a possible mechanism by which reduction of CTNNB1 expression by PPARγ agonists could contribute to inhibition of the loss of cellular attachments, as well as reducing the transcription of tumor-promoting target genes of CTNNB1 such as CCND1 and MYC." (PMID 24672773, 2014).
tumor (continued). "In accordance, we found that numerous E3-skipped variants were differentially expressed between paired tumor and adjacent normal tissues for most patients with cancer, and that E3 skipping is modulated by the PPARγ activator pioglitazone which contributes to cell differentiation and tumorigenesis." (PMID 23614038, 2013). "It has been suggested that PPARγ functions as a tumor suppressor gene; therefore, it is important to understand the complexity of signal transduction pathways and molecular players affected by PPARγ that promote tumor growth, cancer-associated angiogenesis, and metastasis." (PMID 20204067, 2010). "PPARγ ligands have been shown to inhibit proliferation of many tumor cells in vitro and PPARγ may also be implicated in tumorigenesis in vivo." (PMID 19390629, 2009). "In addition to theirmetabolic actions, an emerging area of investigation for PPARγ and PPARδ agonists is their ability to modulate mammary celllineage and genes associated with tumor suppressor function and cell fatedetermination." (PMID 18566686, 2008). "If this were true, this might explain why tumor cells are preferentially susceptible to the PPARγ inhibitors." (PMID 18509498, 2008). "In conclusion, the result showing that PPARγ activation upregulates PTEN,which has also been implicated in tumor-inhibitory or anti-inflammatory actionsof PPARγ, gives credence tothe concept that PPARγ activators induce PTEN duringS6K1 inhibition, and consequently causes TGFβ1 repression." (PMID 18615188, 2008). "On the whole, the evidenceno longer supports the hypothesis that activation of PPARγ promotes tumor formation in mice with germline APC mutations." (PMID 18615192, 2008). "Genomic deletion of WNT5B may imply tumor suppressor function, its loss relieving Wnt signaling of the competing inhibition, and allowing the pathway to exert its negative regulation of PPARγ and C/EBPα." (PMID 18784837, 2008). "PPARγ and PPARδ agonists represent unique classes of drugs that act through their ability to modulate gene transcription associated with intermediary metabolism, differentiation, tumor suppression, and in some instances proliferation and cell adhesion." (PMID 18566686, 2008). "It will be interesting to determine whetherthe PPARγ inhibitors also suppress tumor angiogenesis, and whether the effectsare linked to PPARγ and/or tubulin." (PMID 18509498, 2008). "Furthermore, reductions in mitochondrial function in cancer have been strongly associated with tumor proliferation–PPARγ regulates mitochondrial biogenesis and oxidation by promoting PCG‐1α (PPARGC1A) transcription, thereby enhancing ATP production from fatty acids." (PMID 41236441, 2025). "Our results suggest that AKT1 and PIK3CA may be associated with chemosensitivity in HSCC tumor cells, while PPARG and PTEN might exhibit a correlation with a specific segment of the PI3K/AKT pathway, potentially influencing chemosensitivity in the normal tissue microenvironment of HSCC patients." (PMID 38505269, 2024). "As a cancer-preventative strategy (i.e., prior to the loss of PPARγ expression), the administration of the PPARγ agonists may inhibit the development of a tumor-supportive stroma by targeting angiogenesis, pericyte-to-myofibroblast transition, and adipocyte dedifferentiation." (PMID 37816052, 2023). "This PPARγ loss not only directly liberated EC proliferation but also permitted transition of pericytes towards pro-tumorigenic myofibroblast phenotypes capable of elaborating factors that enhanced both angiogenesis and tumor cell proliferation in vitro and in vivo." (PMID 37816052, 2023). "Studies have also demonstrated that high PPARγ activity is also associated with a consequent increase in arginase 1 expression, suggesting KD-associated fatty acids may have similar effects on the immunosuppressive function of tumor resident macrophages." (PMID 36428642, 2022).